NLRP3 (NLR family pyrin domain containing 3)
Diseases named in the same sentence as NLRP3 in open-access papers (continued):
Sharing a sentence is not in itself a finding about the gene and the disease.
colitis (continued). "A follow-up study found that this direct NLRP3 inhibition by INF39 was more effective than caspase-1 or IL-1β suppression in ameliorating the effects of colitis." (PMID 32456012, 2020). "Proteus mirabilis, through the NLRP3 inflammasome, can contribute to dextran sulfate sodium-induced colitis, indicating that disease outcomes are affected by the various commensal microbiota present in the intestine." (PMID 31387931, 2019). "Mice deficient in NLRP3, Casp1/11, ASC, and IL-1β have all demonstrated an increased susceptibility to DSS-induced colitis, disease exacerbation and more frequent mortality when compared to WT mice." (PMID 30873162, 2019). "3-(2-Oxo-2-phenylethylidene)-2,3,6,7-tetrahydro-1H-pyrazino[2,1-a] isoquinolin-4(11bH)-one, a novel potent Nrf2/ARE inducer, has been found to protect against DSS-induced colitis via inhibiting the NLRP3 inflammasome." (PMID 31885813, 2019). "The dysregulation of NLRP3 inflammasome and its importance in maintaining intestinal health and mucosal immune response have been demonstrated by mice models of colitis." (PMID 30873162, 2019). "For example, mice deficient for NOD-like receptor family pyrin domain containing 3 (NLRP3) were less impressible to acute colitis induced by dextran sodium sulfate (DSS)." (PMID 31849652, 2019). "Further, we found that mouse Irgm1 suppresses the colon inflammation by inhibiting NLRP3 inflammasome in a DSS-induced colitis mouse model." (PMID 30612879, 2019). "Accordingly, we assume that during the induction phase of colitis, total number of M2 macrophages was higher in colons of Gal-3−/− mice due to the reduced activation of NLRP3/IL-1β pathway." (PMID 31336879, 2019). "Undeniably, all studies have clearly indicated that NLRP3 inflammasome plays a key role in the pathogenesis of colitis although the results are still controversial." (PMID 30873162, 2019). "In DSS-induced colitis, the expression of NLRP3 was dramatically higher in the epithelial and stromal cells." (PMID 31885813, 2019). "Administration of the NLRP3 inhibitor MCC95039 attenuated the clinical and histological signs of colitis in Dox-treated iUVRAGFS mice, including weight loss, colon length reduction, histological indices, tissue injury, and inflammatory infiltrates." (PMID 31831743, 2019). "For instance, the pharmacological blockade of NLRP3 signaling has been found to exert beneficial effects in animal models of PD, MS, obesity, type 2 diabetes, arthritis, and colitis." (PMID 31200447, 2019). "In a mouse model of colitis, SCFAs decreased the severity of colitis by activating NLRP3 as well as IL-18 secretion through GPR43 and GPR109A." (PMID 31091682, 2019). "The inhibition of NF-κB signaling and NLRP3 activation has been shown to also exert anti-inflammatory effects in colitis." (PMID 31200447, 2019). "In the inflammatory bowel disease experimental mice model, Irgm1 suppresses the colitis by inhibiting the NLRP3 inflammasome." (PMID 30612879, 2019). "In contrast, recently a number of researches suggested that NLRP3 inflammasome has the function of maintaining gut homeostasis and aiding in protecting from colitis, which have changed past views, suggesting its protective role in intestinal inflammation." (PMID 30873162, 2019). "Given the role of IRGM in inflammatory bowel disease (IBD) and Crohn’s, we utilized the dextran-sulfate (DSS)-induced colitis model to investigate the role of Irgm1 in Nlrp3 inflammasome activation." (PMID 30612879, 2019). "Contrasting phenotypes have also previously been reported from DSS-induced colitis studies in Nlrp3−/− mice." (PMID 31231388, 2019). "By contrast, an intravenous nanoparticle delivery of a miR-223 mimic attenuated DSS-colitis in mice by targeting Nlrp3." (PMID 30755244, 2019). "Taken together, Rev-erbα regulates experimental colitis through its repressive action on the NF-κB/Nlrp3 axis." (PMID 30315268, 2018).
colitis (continued). "Since IL-18 production downstream of the NLRP3 inflammasome is critically involved in protection against colitis and colorectal tumorigenesis, we further determine IL-18 production in colon." (PMID 30382081, 2018). "In this respect, previous studies investigated the role of NLRP3 inflammasome in several experimental models of colitis, highlighting remarkable beneficial effects as a results of its pharmacological modulation." (PMID 30559669, 2018). "Rev-erbα reduces the severity of colitis in mice by repressing NF-κB and Nlrp3 expression, thereby downregulating Nlrp3 inflammasome activity." (PMID 30315268, 2018). "In this study, by using immunohistochemical staining, we firstly detected that the expression of NLRP3 in colonic tissue was elevated in DSS-induced colitis and formononetin reduced the activation of NLRP3 pathway." (PMID 29507526, 2018). "Next, we observed that the expressions of NLRP3, IL-1β, and ASC proteins in colonic tissue were increased, which suggested that the NLRP3 inflammasome pathway was activated in the pathogenesis of colitis in mice." (PMID 29507526, 2018). "The impact of a direct NLRP3 blockade on bowel inflammation was then tested in a murine model of DNBS-induced colitis." (PMID 30559669, 2018). "Collectively, our study for the first time confirmed the protective effects of formononetin on DSS-induced acute colitis via inhibiting the NLRP3 inflammasome pathway activation." (PMID 29507526, 2018). "Taken together, these data indicated an important role of Rev-erbα in regulation of Nlrp3 inflammasome and colitis development." (PMID 30315268, 2018). "Here the authors show REV-ERBα is also involved with linking the circadian system with the inflammatory pathways of an experimental model of colitis through regulation of the NF-κB/NLRP3 axis." (PMID 30315268, 2018). "In line with this concept, the pharmacological inhibition of NLRP3 inflammasome signaling has been shown to exert beneficial effects in several experimental models of colitis." (PMID 30559669, 2018). "Intestinal tract with hyperactive NLRP3 is more likely to maintain homeostasis and has a strong resistance to colitis and colorectal cancer." (PMID 29416535, 2018). "Activation of Rev-erbα prevents DSS-induced colitis in mice through its repressive actions on NF-κB and Nlrp3 inflammasome." (PMID 30315268, 2018). "Together, these novel results demonstrate a new mechanistic role for the SFK-Cbl axis in negatively regulating the NLRP3 inflammasome and reveal the availability of a novel treatment for colitis." (PMID 30382081, 2018). "Further, we revealed a critical role of Rev-erbα in development of experimental colitis through regulation of NF-κB and Nlrp3 inflammasome activities." (PMID 30315268, 2018). "For instance, two recent studies showed that both the in vivo caspase-1 inhibition and the selective blockade of NLRP3 inflammasome complex significantly attenuated colonic inflammation in spontaneous colitis mice." (PMID 30559669, 2018). "Current experimental NLRP3 inhibitors of colitis are applied parenterally, however in our study we have shown effective oral administration with MCC950 which is more clinically desirable than parenteral application." (PMID 29872077, 2018). "Circadian expressions of Nlrp3 and colitis-related inflammatory cytokines were determined in the liver and colon." (PMID 30315268, 2018). "Taken together, Rev-erbα activation prevented DSS-induced colitis via suppression of NF-κB and inactivation of Nlrp3 inflammasome." (PMID 30315268, 2018). "Clock disturbance sensitized mice to experimental colitis by upregulating Nlrp3 inflammasome activity via the Rev-erbα receptor." (PMID 30315268, 2018). "To further explore the effect of MCC950 on NLRP3 inflammasome activation in colitis, we investigated the release of IL-1β in treated Winnie colonic tissue explants by ELISA." (PMID 29872077, 2018).
colitis (continued). "Very similar to our results with MCC950 in Winnie mice, glyburide effectively suppressed NLRP3 inflammasome activation in IL-10−/− mice, leading to attenuation and prevention of colitis." (PMID 29872077, 2018). "In the DSS-induced colitis model, the NLRP3 inflammasome was also indicated as a key mediator in mouse colon inflammation." (PMID 30297787, 2018). "To investigate the mechanism of Huaier-mediated protection from murine colitis, we tested the expression of NLRP3 and IL-1β in colon samples by immunohistochemistry." (PMID 28380426, 2017). "Dimethyloxalylglycine-mediated hydroxylase inhibition ameliorates colitis in mice, downregulates NLRP3 and promotes autophagy." (PMID 28740109, 2017). "In this study, we found that oroxylin A remarkably attenuated the symptoms of murine colitis and decreased the activation of NLRP3 inflammasome induced by DSS in colitis model." (PMID 28938606, 2017). "ROS at high levels can induce many harmful responses, and serve as a common upstream of many inflammatory signaling, such as MMP9, NF-κB, and NLRP3 inflammasome pathway, which contribute much to the initiation and progression of colitis." (PMID 29354126, 2017). "Recent articles have reported that colitis induced by DSS is mediated by the NLRP3 inflammasome in mice." (PMID 28938606, 2017). "Wogonoside, as the glucuronide metabolite of wogonin, at dosages of 12.5, 25 or 50 mg/kg intragastrically, protects against DSS‐induced experimental colitis in mice by inhibiting NF‐κB and NLRP3 inflammasome activation." (PMID 27641629, 2017). "The aim of this study was to investigate the anti-inflammatory effect of a bioactive flavonoid—oroxylin A on the treatment of dextran sulfate sodium (DSS)-induced murine colitis via targeting NLRP3 inflammasome." (PMID 28938606, 2017). "The observation that Nlrp3R258W × Il18−/− mice lose resistance to DSS-induced colitis is probably due to the more predominant and frontier role of IL-18 in the epithelium than NLRP3 in the lamina propria." (PMID 29196621, 2017). "It was reported that Nlrp3-null mice exhibited milder colitis-related symptoms after treatment with DSS, probably due to the reduced secretion of IL-1β." (PMID 28360909, 2017). "The protective effects of flavonoids via NLRP3 inhibition have been shown also in a mouse model of DSS-induced colitis." (PMID 28179906, 2017). "Collectively, these data demonstrated that oroxylin A markedly reduced DSS-induced colitis through inhibiting NLRP3 inflammasome." (PMID 28938606, 2017). "Consistent with a role for MAVS in NLRP3 activation, MAVS-deficient mice exposed to dextran sodium sulphate (DSS)-induced colitis fail to upregulate IL-1β." (PMID 29120406, 2017). "Here we show that hypoxia ameliorates inflammation during the development of colitis by modulating autophagy and mammalian target of rapamycin (mTOR)/NLRP3 pathway." (PMID 28740109, 2017). "It has been documented that the NLRP3 inflammasome plays a critical role in the DSS-induced colitis model." (PMID 28380426, 2017). "At present, the majority of available studies have investigated the role of NLRP3 in several experimental models of colitis, displaying remarkable beneficial effects by the pharmacological modulation of this enzymatic complex." (PMID 28179906, 2017). "Taken together, these results suggest that celastrol-driven autophagy-mediated inhibition of NLRP3 inflammasome is responsible for the protection of mice against DSS-induced colitis." (PMID 28978034, 2017). "The DSS-induced mice colitis model was used to further elucidate the key role of NLRP3 inflammasome in TER protective effects by comparing WT mice and NLRP3−/− mice." (PMID 28553294, 2017). "Of interest, several lines of evidence have shown that various NLRP3-targeting natural compounds are able to exert anti-inflammatory effects on DSS-induced colitis in mice." (PMID 28179906, 2017).
colitis (continued). "Recent evidence has shown that several flavonoid derivatives exerted anti-inflammatory effects on colitis via NF-κB/NLRP3 inhibition." (PMID 28179906, 2017). "In particular, DSS-induced colitis has been largely employed, since in this model lysosomal damage and increased ROS levels can lead to an overactivation of NLRP3 inflammasome." (PMID 28179906, 2017). "In the present study, we found that NLRP3 inflammasome was activated in DSS-induced colitis in C57BL/6 mice." (PMID 28553294, 2017). "To further explore the mechanism of oroxylin A-mediated protection from colitis, we examined the expression of NLRP3 inflammasome in acute colitis." (PMID 28938606, 2017). "Overall, our study found that new type inhibitor MI-2 has certain improvement effect on DSS-induced murine colitis by targeting MALT1-NF-κB and NLRP3 signal pathway, which suggests a new strategy for clinical treatment of colitis." (PMID 27105502, 2016). "The inflammasome NLRP3 plays a crucial role in the pathogenesis of colitis as shown recently in NLRP−/− mice." (PMID 27658624, 2016). "Although several animal studies demonstrated that the NLRP3 inflammasome is involved in the pathogenesis of colitis, few studies exist that assess the role of the inflammasome in IBDs in humans." (PMID 27966619, 2016). "On the other hand, TRIM31 deficiency attenuated the severity of dextran sodium sulfate (DSS)-induced colitis by promoting NLRP3 inflammasome activation, which was reported to be possessing protective roles in the model." (PMID 27929086, 2016). "We demonstrate the MATL1 inhibitors ameliorate clinical symptoms and histopathologic features of DSS-induced colitis via inhibiting NF-κB and NLRP3 inflammasome activation in macrophage in vivo and in vitro." (PMID 27105502, 2016). "Wogonoside, another major component in Huangqin, has been shown to inhibit the activation of NF-kB and NLRP3 inflammasomes in DSS-induced colitis and colitis-associated tumorigenesis in mice." (PMID 27557503, 2016). "Our study here characterized that inhibitors of MALT1, would be safe and potent for the treatment of DSS-induced murine colitis by inhibiting NF-κB and NLRP3 inflammasome activation in macrophage." (PMID 27105502, 2016). "It was recently reported that oral administration of titanium dioxide (TiO2) nanoparticles aggravated the severity of IBD through a mechanism involving the activation of the NLRP3 inflammasome in DSS-induced colitis mice or UC patents." (PMID 28119697, 2016). "One obvious target of mitochondrial antioxidants is the NLRP3 inflammasome, and, indeed, another mitochondrial rechargeable antioxidant, MitoQ, was reported to suppress activation of the NLRP3 inflammasome in a model of dextran sulfate-induced colitis." (PMID 27293517, 2016). "Taken together, these data suggest that inducing autophagy at least partly contributed to CB2R-mediated suppression of NLRP3 inflammasome activation in mice peritoneal macrophages as well as colon of experimental colitis mice." (PMID 27611972, 2016). "Colitis was induced in wild-type (WT) and Nlrp3−/− mice by treatment with dextran sulphate sodium (DSS)." (PMID 27610005, 2016). "In our study, we observed a similar reciprocal relationship between NLRP3 and IL-15, where the expression of NLRP3 protects mice from experimental colitis and its deletion leads to increased IL-15 expression and enhanced intestinal inflammation." (PMID 27610005, 2016). "We and others have reported previously a protective role of the NLRP3 inflammasome in the maintenance of intestinal homeostasis in the context of experimental colitis." (PMID 27610005, 2016). "TRIM31 expression was downregulated in the DSS-induced colitis model, and NLRP3 expression was upregulated accordingly." (PMID 27929086, 2016). "In TRIM31−/− mice, NLRP3 expression was further increased in the colon of DSS-induced colitis model." (PMID 27929086, 2016).
colitis (continued). "Several studies have revealed that the NLRP3 inflammasome is involved in murine experimental colitis, and that stimulation of the inflammasome was modulated by mitochondrial ROS." (PMID 26484345, 2015). "A recent report suggested that uncontrolled NLRP3 inflammasome activation promotes the spontaneous colitis observed in Il10−/− mice." (PMID 26412089, 2015). "Here we show that single infusion of apoptotic cells clearly ameliorate clinical and histological colitis via inhibition of NF-κB and NLRP3 inflammasome and thus, represent a novel therapeutic approach." (PMID 25822487, 2015). "Despite these convincing data, conflicting observations suggested opposite dependency in DSS colitis on the NLRP3 inflammasome." (PMID 25822487, 2015). "In an infectious model of colitis with C. rodentium, early activation of the NLRP3 or NLRC4 inflammasomes within the IECs limit pathogen colonization and prevent pathology in mice." (PMID 24886810, 2014). "To study the in vivo role of the ASC and NLRP3 molecules in more depth we here made use of two different lethal S. Typhimurium models modeling typhoid and colitis disease." (PMID 25115174, 2014). "Recent studies examining the molecular mechanisms by which NLRP3 and caspase-1 control integrity of the intestinal epithelium during experimental colitis point to a critical role of NLRP3 in gut mucosal immune homeostasis." (PMID 25071778, 2014). "The authors found that mice deficient for NLRP3 inflammasome components including NLRP3, ASC or caspase-1 had severe colitis and increased tumorigenesis in AOM/DSS colon cancer model." (PMID 25120559, 2014). "We sought to characterize the role of ASC and NLRP3 in two different murine models (typhoid and colitis) of systemic Salmonella infection." (PMID 25115174, 2014). "Several studies showed that mice deficient for inflammasome components including NLRP3, ASC, and caspase-1 were highly susceptible to acute colitis induced by DSS, indicating the protective role of inflammasome in acute colitis." (PMID 25120559, 2014). "More recently, this protective role of NLRP3 against DSS colitis was also demonstrated by yet another independent group." (PMID 23606794, 2013). "After administration of DSS, NLRP3 knockout mice developed less severe colitis than wild-type mice and produced lower levels of proinflammatory cytokines in colonic tissue." (PMID 23606794, 2013). "Accordingly, mice deficient in caspase-1, ASC, NLRP3, NLRP6, NLRP12, and NLRC4 all have increased colitis and subsequent development of colorectal cancers in gut irritant models." (PMID 24409181, 2013). "For example, dextran sodium sulfate-mediated colitis and MSU-induced joint inflammation in a murine model of gout are less severe in mice deficient in caspase-1 or NLRP3." (PMID 23977231, 2013). "To clarify the mechanism of MitoQ in attenuation of colitis, we investigated the function of the NLRP3 inflammasome." (PMID 23915129, 2013). "Importantly, 2',4'-DHC treatment inhibited NLRP3 inflammasome, while also balancing gut microbiota in colitis mice." (PMID 41727437, 2026). "Recent studies elucidate the potent protective effects of Ruscogenin against DSS-induced colitis, demonstrating its ability to alleviate the condition in mice by inhibiting the activation of the NLRP3 inflammasome and the caspase-1-dependent canonical pyroptosis." (PMID 40271055, 2025). "Similarly, a homogalacturonan-enriched pectin-based hydrogel alleviated the effects of colitis by reducing inflammation via the NF-κB/NLRP3 axis." (PMID 40283898, 2025). "Furthermore, IL-18 has been shown to be essential for mucosal homeostasis: mice deficient in Nlrp3, Pycard/Asc, caspase-1, IL-18, or IL-18R—all components of the inflammasome pathway—are highly susceptible to DSS-induced colitis." (PMID 40869366, 2025). "Ruan and colleagues have identified pterostilbene analogs as novel NLRP3 inflammasome inhibitors that may be used to treat mice’s DSS-induced colitis." (PMID 40534879, 2025).